CRP (C-reactive protein)
Diseases named in the same sentence as CRP in open-access papers (continued):
Sharing a sentence is not in itself a finding about the gene and the disease.
Crohn disease (continued). "The different degrees of endoscopic activity were correlated with the following indexes: Crohn’s disease activity index (CDAI), fCal, serum C-reactive protein (CRP), and haemogram." (PMID 32054445, 2020). "We investigated the rate of continuous treatment of mesalazine granules and examined the changes in Crohn’s Disease Activity Index (CDAI) and serum C-reactive protein (CRP), albumin, and hemoglobin (Hb) levels 2 years after the switch." (PMID 33288852, 2020). "The variables used were Crohn’s Disease Activity Index (CDAI) for patients with Crohn’s Disease (CD) and fecal calprotectin (FC), C-Reactive Protein (CRP), and albumin (ALB) for patients with IBD." (PMID 33375314, 2020). "The variables used were Crohn’s disease activity index (CDAI), C-reactive protein (CRP), and erythrocyte sedimentation rate (ESR)." (PMID 31689999, 2019). "The disease activity assessed by the Crohn’s disease activity index (CDAI) was 196.6 ± 22.8 points and C-reactive protein was 3.9 ± 1.3 mg/dl." (PMID 31852983, 2019). "In another small-scale study, increased inflammation was found in 43 subjects with active Crohn’s disease (CD), as indicated by high levels of plasma TNF-α and CRP, compared with healthy controls." (PMID 31213029, 2019). "Preoperative CRP (c-reactive protein) and ESR (erythrocyte sedimentation rate) were higher than normal range, implying inflammatory events in patients with Crohn’s disease." (PMID 28852175, 2017). "In conclusion, the study presented here finds statistically significant improvements in Hb, CRP, ESR, and WBC, postoperatively and at long-term follow-up in patients with ileocaecal Crohn's disease who underwent early ileocaecal resection." (PMID 28776001, 2017). "C-reactive protein (CRP), erythrocyte sedimentation rate (ESR), and globulin were positively correlated to Crohn disease activity index (CDAI), Bath AS disease activity index, and Bath AS functional index(BASFI) scores (r = 0.73–0.93, P < 0.05)." (PMID 27428240, 2016). "Crohn’s disease activity index (CDAI), Sutherland disease activity index for UC (UCAI) and C-reactive protein (CRP) of the IBD patients are normally used to evaluate the disease activity." (PMID 26572590, 2015). "Crohn’s Disease Activity Index (CDAI) scores were 250–450 and C-reactive protein >7.5 mg/L at study entry." (PMID 23527300, 2013). "Clinical response and remission were observed in 50% and 41% of cases, respectively, with significant reductions in the Simple Endoscopic Score for CD (SES-CD) (from 14.0 to 6.0, p = 0.0005), Crohn’s disease patient-reported outcome-2 score (PRO-2), and C-reactive protein (CRP) levels." (PMID 40001525, 2025). "A latent class mixed model was employed to identify distinct trajectories of C-reactive protein (CRP) and fecal calprotectin (FCP) levels in 256 and 635 patients with Crohn’s disease (CD) and ulcerative colitis (UC), respectively, from a tertiary hospital cohort." (PMID 40314771, 2025). "Conversely, the recently published guidelines on the use of biomarkers in Crohn’s disease list three biomarkers for the routine monitoring of patients; calprotectin, erythrocyte sedimentation rate (ESR), and C-reactive protein (CRP), with less reliance on colonoscopy." (PMID 38391544, 2024). "Various measures, including Crohn’s Disease Activity Index (CDAI), Mayo Score/ Disease Activity Index (DAI), and C-reactive protein (CRP) levels, were taken at baseline and week 14 to assess the efficacy of the treatments." (PMID 38985232, 2024). "Binomial logistic regression analysis identified seven clinical variables with a p-value less than 0.01, including Biomarker (B), Waist-to-Height Ratio (WHtR), Intestinal obstruction, Albumin (ALB), Crohn's Disease Activity Index (CDAI), Myocardial Flow Index (MFI), and C-reactive protein (CRP)." (PMID 38480778, 2024). "The CRP responses more modest in UC compared to that in Crohn’s disease, with more than 15% of patients with UC showing no CRP response." (PMID 39208267, 2024).
Crohn disease (continued). "They reported that the indices of clinical remission and response, with a simple endoscopic score for CD (SES-CD), dropped from 17 to 5, the Crohn’s disease activity index score (CDAI) dropped from 228 to 200, and C-reactive protein (CRP) remained at 0.20–0.30." (PMID 39152520, 2024). "Crohn’s disease patients tested for the presence of C-reactive protein (CRP) in blood plasma showed no significant increase in the concentration of bacterial metabolites." (PMID 39796508, 2024). "Clinical response (100-point decrease in Crohn’s Disease Activity Index [CDAI] score), clinical remission (CDAI score of <150), steroid-free clinical remission, C-reactive protein, endoscopy, physician global assessment, and adverse drug reactions (ADRs) were evaluated through 52 weeks." (PMID 36777365, 2023). "Other factors that can lead to high clearance include male gender, induction compared to maintenance therapy, prior biologic therapy, an increased Crohn’s disease activity index (CDAI), as well as elevated fecal calprotectin, C-reactive protein (CRP) and erythrocyte sedimentation rate (ESR)." (PMID 38002743, 2023). "C-reactive protein to albumin ratio (CAR), a composite indicator of inflammation and nutritional status, has recently been recognized as an independent prognostic marker in malignancy, Crohn’s disease, critically ill patients and vasculitides." (PMID 37223604, 2023). "This study aims to identify the role of IUS, contrast-enhanced ultrasound (CEUS) and MRE in evaluating ileal CD activity, using clinical severity scores (Crohn’s disease activity index—CDAI, Harvey–Bradshaw index—HBI) and faecal calprotectin or C-reactive protein (CRP) levels as reference methods." (PMID 37629610, 2023). "For instance, MALT1 is upregulated in Crohn’s disease patients and ulcerative colitis patients compared to HCs, and it relates to elevated CRP, ESR, Crohn’s disease activity index score, or mayo score in the active patients." (PMID 35967391, 2022). "This study examined associations between dietary intake and gut and systemic inflammation assessed by fecal calprotectin ≤ or > 100 μg/mg (FCP), C-reactive protein ≤ or > 5 mg/L (CRP) and serum cytokine profiles in Crohn’s disease (CD) patients in clinical remission." (PMID 33462267, 2021). "Moreover, both in Crohn’s disease as well as in UC, HHMQoL-IBD score was related with CRP, a marker of disease activity." (PMID 35010375, 2021). "CRP is one of the most used biomarkers in inflammatory conditions, but its levels are not often correlated to UC activity, unlike Crohn’s disease." (PMID 33897440, 2021). "Third, CRP is not a perfect proxy for biological remission given that up to 20% of patients with Crohn disease do not experience elevated CRP levels during a flare." (PMID 31074823, 2019). "In a prospective study of 38 patients from China, there was a significant reduction in the Crohn’s Disease Activity Index (CDAI) score and C-reactive protein (CRP) levels after 8 weeks of EEN along with improvement in nutritional status, and reduction in visceral fat area." (PMID 31352652, 2019). "I also made the striking discovery that the CRP response in ulcerative colitis, which, in 1975, also had not previously been reported, was completely different from Crohn's disease." (PMID 30459761, 2018). "The results of this pilot study imply that 18F-FDG PET/MRE metrics of MIV and ADC have an added value to MaRIA score in discriminating patients with active from nonactive Crohn's disease based on fecal calprotectin and CRP levels." (PMID 29097934, 2017). "Historically, clinical indices (Crohn's disease activity index (CDAI), Harvey-Bradshaw index (HBI)) and systemic inflammatory markers (C-reactive protein (CRP)) have been used to assess disease activity in CD and have been found to correlate with levels of vitamin D." (PMID 29348747, 2017).
Crohn disease (continued). "Finally, SDC-1 efficacy in predicting disease activity was evaluated by performing correlation analysis between SDC-1 and C-reactive protein (CRP) and Crohn's disease activity index (CDAI)." (PMID 26294905, 2015). "Crohn's disease endoscopic index of severity (CDEIS) value correlated positively with macrophage TIMP-1 and stromal TIMP-3 and negatively with epithelial TIMP-3 which also negatively correlated with C-reactive protein values (CRP)." (PMID 25948887, 2015). "The results of this nationwide real-world study demonstrate that induction and post-induction serum vedolizumab concentrations are not consistently associated with biochemical (CRP and FCP) normalization in individuals with Crohn’s disease and ulcerative colitis." (PMID 39139218, 2024). "In any case, the assessment of AIF-1 in serum could be of interest to monitor Crohn’s disease in patients, especially in whom CRP does not increase due to the existence of low-expression SNP polymorphisms." (PMID 35327530, 2022). "The aim of this study was to determine whether postoperative CRP levels can be used to rule out anastomotic leaks in patients with Crohn’s disease and to set CRP threshold values for this population." (PMID 35055369, 2022). "Furthermore, MALT1 was positively related to C‐reactive protein (CRP), TNF‐α, IL‐17A, and mayo score in A‐UC patients; positively correlated with CRP, erythrocyte sedimentation rate, TNF‐α, and Crohn's disease activity index score in A‐CD patients." (PMID 34997981, 2022). "Recent clinical trial reports have demonstrated that RHB-104 has shown a consequential improvement in CD biomarkers of inflammation such as C-reactive protein (CRP) and Crohn’s disease activity index (CDAI) with or without concomitant anti-TNF-α or immunosuppressive therapy." (PMID 33217961, 2020). "However, other data from the literature have shown that CRP is not as useful in UC, as it is in Crohn's disease, for the assessment of disease activity, with the exception of acute severe colitis." (PMID 32677804, 2020). "However, to my surprise, in 1975, CRP measurements had not been reported in either Crohn's disease or ulcerative colitis and I set out to do this for the first time." (PMID 30459761, 2018). "JKAP expression was decreased in inflamed mucosa of active IBD patients and was negatively correlated with disease activity [Crohn’s disease activity index (CDAI), Mayo index, C-reactive protein, and erythrocyte sedimentation rate], interleukin-17, and tumor necrosis factor (TNF)-α levels." (PMID 28725226, 2017). "The effectiveness of therapy was evaluated individually using the Crohn’s Disease Activity Index (CDAI) in patients with CD or the Mayo Scoring System (MSS) in patients with UC, and also by endoscopy and C-reactive protein (CRP) values, after 14 weeks of therapy." (PMID 27002981, 2016). "Moreover, with a higher negative predictive value, Crohn’s disease diagnosis may be excluded in patients with non-specific gastrointestinal symptoms and biomarkers such as C-reactive protein (CRP) and fecal calprotectin with normal values." (PMID 34377195, 2021). "In a study from our group using THC rich cannabis in patients with Crohn’s disease, we found significant clinical improvement, reduction of CDAI and improved quality of life, but no change in CRP." (PMID 33571293, 2021). "Baseline 25-vitD levels did not correlate with faecal calprotectin, C-reactive protein (CRP), Harvey-Bradshaw Index (HBI), or Crohn's Disease Activity Index (CDAI) scores (data not shown)." (PMID 28412753, 2017). "While the correlations were not as strong in Crohn’s disease, urinary GSA significantly correlated with other biomarkers, including ELISA fMPOp (r = 0.25, P = .01), ELISA fMPOa (r = 0.27, P < .01), fCal (r = 0.33, P < .01) and CRP (r = 0.29, P < .01)." (PMID 40411448, 2025).
Crohn disease (continued). "However, an important point to be noted is that although CRP and FCP are considered important in CD, the quantitative relationship between the markers and the clinical score (e.g., Crohn’s Disease Activity Index (CDAI), is not well established." (PMID 32822115, 2021). "Additionally, patients with a serum level above 75 nmol/L have significantly lower serum levels of C-reactive protein (CRP, a marker of inflammation) and a non-significant decrease in disease activity as measured with Crohn’s Disease Activity Index." (PMID 28163705, 2016).
Hyperglycemia (313 papers, 2006 to 2026). An increased concentration of glucose in the blood. "Key risk factors included use of multiple vascular accesses, hyperglycemia, and elevated C-reactive protein." (PMID 41010430, 2025). "The management of hyperglycemia, with minimal risk of pulmonary complications or fatal outcomes (evidenced by low levels of fibrinogen, C-reactive protein, procalcitonin, and D-dimers), was closely associated with IL-6 levels at the time of hospitalization." (PMID 40134446, 2025). "CRP levels demonstrated a moderate association with hyperglycemia, with obese patients showing higher levels (55 ± 15 mg/L) than their non-obese counterparts (48 ± 12 mg/L, p = 0.03)." (PMID 40002762, 2025). "The presence of hyperglycemia at follow-up was associated with both on-admission and peak serum glucose levels of ≥100 mg/dL, as well as with a longer stay, higher CRP levels, and antibiotic use during index admission." (PMID 38929473, 2024). "Elevated plasma CRP and hyperglycaemia were both associated with increased risk of IHD and CVD death." (PMID 38730445, 2024). "Enrichment of Fusobacterium was identified in the fecal microbiome of pregnant mothers who gave birth prematurely, mothers with pre-eclampsia, and was associated with C-reactive protein levels in the blood of mothers with hyperglycemia." (PMID 39473842, 2024). "Hyperglycaemia has been shown to associate with increased concentrations of inflammatory markers such as plasma C-reactive protein (CRP)." (PMID 38730445, 2024). "For instance, hyperglycemia was associated with both high serum CRP levels and increased periodontal damage." (PMID 37038173, 2023). "In this study, intermediate hyperglycaemia caused a significant increase in CRP, TNF-α and IL-6 concentration in the PD compared to the NPD group." (PMID 38024366, 2023). "Hyperglycemia on admission was correlated with a lower PFR, elevated levels of NLR, CRP, IL-6, and TyG index, while hyperglycemia during hospitalization was associated with increased levels of CRP and TyG index." (PMID 37515156, 2023). "Similar associations were documented for increased levels of CRP and TyG index and hyperglycemia during hospitalization." (PMID 37515156, 2023). "Despite these suggestive findings in healthy individuals, we did not observe an association between acute or acute-on-chronic hyperglycaemia and CRP levels during admission." (PMID 38202252, 2023). "Our retrospective study in GBS patients showed that FPG hyperglycaemia and increase of CRP at admission were positively associated with the need for mechanical ventilation." (PMID 35677334, 2022). "After 8 years of follow-up, the results of the current study revealed that high levels of inflammation (represented with hs-CRP) and hyperglycemia (represented with hbA1c) were risk factors that predict a higher risk of ACD." (PMID 35172860, 2022). "It is worthy of being noted that in the diabetic population, persistent hyperglycemia (over 96 h after admission) was associated with adverse clinical outcomes and abnormal levels of CRP." (PMID 36344933, 2022). "In this study, we found a similar observation that hyperglycaemia and increase of CRP at admission were positively associated with mechanical ventilation." (PMID 35677334, 2022). "Higher levels of salivary CRP and insulin (OR 4.97 [95%CI: 1.66,14.90]; p = 0.004, OR 2.64 [95%CI: 1.09,6.38]; p = 0.03, respectively) were associated with intermediate hyperglycemia." (PMID 35757631, 2022). "We also found that blood glucose level was positively correlated with the serum concentration of IL-6 and CRP level, suggesting that hyperglycemia aggravated the systemic inflammatory response caused by SARS-CoV-2." (PMID 37359706, 2022). "Both in vitro and in vivo studies have linked hyperglycaemia with elevated levels of C-reactive protein (CRP), interleukin-6 (IL-6), and TNF-α." (PMID 33466656, 2021).